CDKN2A (cyclin dependent kinase inhibitor 2A)
Diseases named in the same sentence as CDKN2A in open-access papers (continued):
Sharing a sentence is not in itself a finding about the gene and the disease.
tumor (continued). "Two high-risk genes have been identified: the cell cycle regulator CDKN2A on chromosomal band 9p21 and the cyclin-dependent kinase-4 (CDK4) on chromosomal band 12p14, the products of which are known to be components of potent tumour-suppression pathway." (PMID 18612309, 2008). "One tumor had CDKN2A homozygous deletion and CCNE1 amplification." (PMID 18549475, 2008). "Thus, of a total of 26 tumours investigated, 15 (58%) displayed a heterozygous deletion of the region covering the CDKN2A locus, and 3 (12%) showed a homozygous deletion." (PMID 18071362, 2008). "For example, expansion of a CDKN2A abnormal clone that is otherwise genetically stable may homogenize the neoplasm, minimizing diversity on which natural selection might act to promote progression." (PMID 17326708, 2007). "The methylation status of the 5' CpG island of the CDKN2A gene was studied in all 15 tumours retaining only one allele of CDKN2A as well as in the six tumours showing no significant expression of transcript despite their retaining both CDKN2A alleles." (PMID 9000591, 1997). "Our present study demonstrated that CDKN2A expression was positively correlated with the infiltration levels of CD4+ T cells, macrophages, and cancer-associated fibroblasts, suggesting its apparent potential role in promoting tumor progression through remodeling the immune microenvironment." (PMID 41614944, 2026). "In melanoma, familial mutations in CDKN2A, RB1, and TERT attenuate senescence, enabling uncontrolled proliferation, whereas ERK5 inhibition triggers senescence via LTBP1-mediated TGF-β1 activation, which suppresses tumor growth and enhances immunotherapy response." (PMID 40781676, 2025). "Although the CDKN2A gene is frequently involved somatically in melanoma, pancreatic cancer, and other tumors, to our knowledge the specific p16-Leiden variant has never been identified as a purely somatic variant in any tumor." (PMID 40917369, 2025). "Future studies should investigate whether OC disrupts this PAR-2/RAC1/β-catenin axis in IDH-mutant CHS models, leveraging its dual capacity to downregulate PAR-2 and preserve repressive H3K27me3 epigenetic marks to counteract CpG island hypermethylation at tumor suppressor loci such as CDKN2A." (PMID 40564985, 2025). "Thus, in the adagrasib resistant SW1573 model harboring KRAS-G12C and CDKN2A homozygous loss, adagrasib and abemaciclib combination, but not adagrasib alone, mediated anti-tumor effects and survival prolongation." (PMID 40317086, 2025). "Similarly, the proportion of EGFR+ tumor cells had a predictive AUC of 90.1% for EGFR amplification, with the best cutoff point at 14.3%, and the proportion of CDKN2A+ tumor cells had a predictive AUC of 79.4% for CDKN2A deletions with the best cutoff point of 0.5%." (PMID 40264576, 2025). "Notably, CDKN2A, a well-known tumor suppressor gene, showed high expression in tumor tissues." (PMID 39895793, 2025). "While CDKN2A is a tumor suppressor, its robust protein expression is a recognized biomarker of oncogene-induced cellular senescence or a dysfunctional cell cycle checkpoint in many cancers, a state that could be exacerbated by the diabetic metabolic environment." (PMID 41244925, 2025). "In addition to TRIM24::NTRK2 and CDKN2A/B HD, a SLC6A14 missense variant (p.R614H) of unknown significance (VUS) was present in all six tumor specimens." (PMID 41331048, 2025). "Similarly, tumor epithelial cells expressing CDKN2A exhibited elevated Wnt pathway activity." (PMID 38888512, 2024). "Interestingly, in both the tumor and the PDX, the first hit is represented by a large ch9p deletion, involving the 9.p21 locus that includes the CDKN2A gene, whereas the second hit in the tumor is represented by a further genomic deletion (135 Kb deletion) leading to homozygous loss." (PMID 39283723, 2024).
tumor (continued). "Moreover, we can speculate that discrepancies in CDKN2A protein expression may result from the changes in transcription and translation processes and may also be due to tumor heterogeneity." (PMID 39590385, 2024). "Consequently, tumor epithelial cells expressing CDKN2A exhibited elevated EMT scores." (PMID 38888512, 2024). "One theory is that these lesions may have genome instability and are more prone to progress to malignancy through acquiring further genetic aberrations such as copy number changes or CDKN2A inactivation, although the true behavior of these neoplasms is a question that remains to be answered." (PMID 38390852, 2024). "Our findings suggested that high levels of CDKN2A, BIRC5, and SPP1 were associated with poor overall survival in patients with HCC, suggesting that BIRC5, CDKN2A, and SPP1 are associated with HCC progression and could be used as tumor biomarkers in patients with HCC." (PMID 39042294, 2024). "Our findings in this research showed that CDKN2A might be utilized as a marker to identify cancer patients as it could be used to differentiate between cancer tissue samples and control groups in a variety of tumor forms." (PMID 38206516, 2024). "Furthermore, we reported a positive correlation between the CDKN2A protein level in the tumor samples and years of smoking, while in the marginal samples we observed a positive correlation with the number of cigarettes smoked per day and an average positive correlation with pack-years." (PMID 39590385, 2024). "However, the effects of CDKN2A appear to vary depending on the tumor type." (PMID 38888512, 2024). "In the present study, we proposed an alternative perspective on the tumor-promoting role of CDKN2A, suggesting that it may achieve this function by modulating intracellular copper ion concentration, potentially through the regulation of copper ion transport channel proteins." (PMID 38888512, 2024). "Finally, losses of CDKN2A in these cell lines or CDKN2A/RB1 in these tumors in the H2 group may also contribute to tumor development and modulate drug responses." (PMID 37369741, 2023). "Additionally, cases with intratumoral heterogeneity may only harbor biallelic inactivation of CDKN2A in a subset of tumor cells." (PMID 36723772, 2023). "Therefore, some tumours that are CDKN2A/B intact but have suppressed CDKN2A/B expression will have no immunoreactivity on p16 IHC but retain other genes that may confer a less aggressive phenotype." (PMID 37504251, 2023). "It is possible that CDKN2A heterodel detected on bulk CNV analysis represents a transient state of a subclone that has acquired a focal CDKN2A deletion en route to becoming a tumor with homozygous CDKN2A loss as opposed to these cases existing in a true clonal heterozygous state." (PMID 37093270, 2023). "Moreover, further analysis was made to investigate the mRNA expression level of CRGs between normal and CRC samples, and we found that the expressions of FDX1, DLD, DLAT, PDHB, and MTF1 were significantly decreased, whereas LIPT1, GLS, and CDKN2A were significantly upregulated in tumor samples." (PMID 37006250, 2023). "As a tumor suppressor gene, its expression is low in many tumors, but, interestingly, its overexpression has also been reported in many cancers, and such high expression of CDKN2A may affect the clinical outcome of the patient." (PMID 38188288, 2023). "However, given the evidence that CDKN2A/B HD alters tumour biology (increased angiogenesis and cell growth), we cannot assume that these tumours will be as susceptible to temozolomide as their non-deleted counterparts." (PMID 37504251, 2023).
tumor (continued). "Similarly, the tumour suppressor CDKN2A are also categorized c-MYC target genes could control the G1/S transition 47-48." (PMID 37215441, 2023). "Importantly, correlation analysis revealed the MGPSs were positive correlated with the expression of CDK4/6 and negatively correlated with expression of CDKN2A/B, supporting the deletion of CDKN2A/B contribute to the tumor cell proliferation through activating CDK4/6." (PMID 36720864, 2023). "We boldly inferred that there may be a positive regulatory relationship between CDKN2A and DDX11-AS1, and that silencing DDX11-AS1 can indirectly inhibit the CDKN2A expression, thereby increasing the role of copper loading in tumor cells, promoting cuproptosis, and increasing tumor cell apoptosis." (PMID 36891559, 2023). "Therefore, this study attempted to investigate whether CDKN2A can be used as a robust tumor marker and play a role in pan-cancer immunotherapy, thereby providing some clues for tumor immunotherapy strategy." (PMID 36961395, 2023). "Moreover, HPV+ HNSCC exosomes, which carried E6/E7 oncoproteins, p16INK4a/CDKN2A (cyclin-dependent kinase inhibitor 2A) and survivin, promoted DC maturation triggering the activation of anti-tumour immune responses, thereby improving outcome in patients with HPV+ve HNSCC." (PMID 36980527, 2023). "Both his relapsed cf-tDNA sample and recurrent tumor tissue were detected to have newly emerging CDKN2A:p.L16Pfs*9 and PDGFRA:p.V536E mutations compared to the initial tissue, indicating that the relapsed tumor had evolved more malignant branches featured with CDKN2A loss." (PMID 37920153, 2023). "Hence, we can conclude that CDKN2A genetic alterations can generally direct tumor-infiltrated CD8 T cells to the exhaustion status where some of the analyzed human tumors experienced also a reduction in the CD8 infiltration while others did not experience that reduction." (PMID 37626750, 2023). "Nevertheless, volumetric tumor size alone is not sufficient to predict CDKN2A mutation status, as shown by the largely overlapping boxplots and investigation of more complex imaging features like radiomics might be of interest in further studies." (PMID 38135704, 2023). "However, homozygous deletion of CDKN2A is observed in 50% of human tumor cell lines." (PMID 37876534, 2023). "We first examined genes that may render cell-growth advantage through analysis of our CRISPR/Cas9 perturbation screen in JeKo-1 cells and found that many critical tumor suppressors were located on chr9, including CDKN2A, SMARCA2, FBXO10, and TOR1B (z score ≥ 1)." (PMID 34882582, 2022). "Notably, CDKN2A, a typical tumour-suppressor gene, was the shared gene in these four cohorts." (PMID 34980126, 2022). "Furthermore, Cdkn2a-Cdkn2b, which is a rapidly evolving locus that contains critical tumor suppressor genes, has signals of positive selection and a unique structure in naked mole-rats, providing extra cancer protection through specific products generated by alternative splicing." (PMID 36534348, 2022).
tumor (continued). "Interestingly, we also compared their expression levels between tumor and normal tissues and found that the expressional changes were complex, especially significantly upregulated genes (CDKN2A, MYCN, PLK1, and TERT) and some downregulated signatures (AXL, ID1, and TLR3)." (PMID 35754848, 2022). "Additionally, univariate and multivariate Cox regression analyses were both used to assess whether the 21 CDKN2A-derived genes signature was an independent prognostic factor for other features, including age, sex, metastasis status, tumor stage, and so on." (PMID 36052076, 2022). "For palbociclib, we observed a significant tumor response for one of two models harboring the deletion of CDKN2A/2B (p = 0.02), and no significant tumor response in the PBRM1-mutated PDX; for volasertib, we did not observe any response in the three tested models." (PMID 36505864, 2022). "Additionally, the hypermethylation of CDKN2A was positively correlated with the tumor progression, verifying that CDKN2A may be a crucial impact factor in the stage and grade of BRCA." (PMID 36052076, 2022). "Interestingly we found that CDKN2A,FADD,GATA3,MYC were highly variable between gain and loss in CNV, while at the mRNA expression level these same NRGS were also found to be significantly different in normal tissues compared to tumor tissues." (PMID 35478725, 2022). "Mechanistically, DEFA5 induces cell cycle arrest by binding to BMI1, reducing its binding to the CDKN2a locus and upregulating the expression of the cyclin-dependent kinase inhibitors p16 and p19, therefore significantly increasing the number of cells in the G1 phase and inhibiting tumor growth." (PMID 36275647, 2022). "Interestingly, genes encoding CDK inhibitors, such as CDKN1A (p21Cip1), CDKN2A (p16INK4A), CDKN2C (p18INK4C) were downregulated in our CNFPA, which is consistent with a cyclin-mediated oncogenic mechanism, whereby these proteins act as tumor suppressors." (PMID 35260162, 2022). "Unfortunately, mutations or loss of function in the Cdkn2a gene eventually leads to tumor formation, making it not feasible to perform limiting dilution experiments in 1-year-old Cdk2na knockout mice and also making it less than ideal to target therapeutically." (PMID 35311644, 2022). "An expanding knowledge of molecular features, such as CDKN2A heterogenous deletion, may then become factors that influence the utilisation of a more aggressive approach with repeat craniotomy seeking maximal tumour reduction prior to delivery of IMRT." (PMID 35027006, 2022). "Combining Sox2 overexpression with tumour suppressive Pten and Cdkn2a mutations leads to LUSC-like tumours regardless of whether the Cre-driver gene is expressed by basal, club or AT2 cells." (PMID 33435818, 2021). "However, Cdkn2a loss, affecting both p16INK4a and p19ARF expression, resulted in tumor relapses with EMT features, without reactivation of the Wnt pathway." (PMID 33445626, 2021). "Besides, we observed the deletion peaks of tumor suppressive genes such as CDKN2A/CDKN2B and PTEN." (PMID 33658560, 2021). "Therefore, CDKN2A has potential as a therapeutic target for tumor treatment." (PMID 35004697, 2021). "Furthermore, a growing body of evidence implicates CDKN2A LOF in tumor biology and outcome." (PMID 34625620, 2021).
tumor (continued). "The only shared alteration between all tumors was the loss of the CDKN2A/2B genes that resulted from chromosome 9 rearrangements in all non-related tumors, but which is not constitutional because it is not observed in the non-tumor tissues." (PMID 33963205, 2021). "Single deletion of Cdkn2b (codes for p15Ink4b) in mice does not result in any significant tumor susceptibility, while Cdkn2a (codes for p16Ink4a and p19ARF) global knockout animals reach adulthood without any major developmental defects, but begin to spontaneously form tumors at 20 weeks of age." (PMID 33078209, 2021). "Indeed, the status of the CDKN2A gene is highly variable, with no loss, hemizygous and homozygous losses within the same tumor." (PMID 34277422, 2021). "The association of CDKN2A deletion with higher copy number burdens might indicate a beneficial effect of immune checkpoint inhibitors, but the co-deletion of IFN type I could enhance tumour cell evasion of immune surveillance." (PMID 34580349, 2021). "We stratified CDKN2A/MTAP expression into increasing quartiles and first examined whether changes in CDKN2A/MTAP expression were associated with TME immune cell composition, PD-L1 expression on immune and tumor cells and the immune phenotypes." (PMID 34556668, 2021). "Therefore, we assumed that sarcomatoid HCC had a larger tumor size than non‐sarcomatoid HCC, which was reported in this study and the previous ones, maybe at least partially due to the CDKN2A mutation." (PMID 34331411, 2021). "CDKN2A deletion may also occur as secondary event in tumor progression." (PMID 32514758, 2020). "Furthermore, CDKN2A was thought to inhibit tumor growth; however, the mechanisms that promote tumor progression remain unclear." (PMID 33109128, 2020). "Unlike the two Ion Torrent platforms, in one tumor sample the Illumina platform called two different genetic variants [NM_001195132: c.35C > T (p.Ser12Leu) and c.35delC (p.Ser12TrpfsTer14)] in the same position of a CDKN2A amplicon (AMPL-225530996)." (PMID 33317587, 2020). "CDKN2A deletion shows no relevant association with tumor phenotype and patient outcome." (PMID 32256975, 2020). "Finally, promoter hypermethylation of the cyclin-dependent kinase Inhibitor 2A (CDKN2A) gene, which acts as tumor-suppressor by regulating cell cycles through encoding the p16INK4a and p14ARF proteins, has also been reported in HGOS and suggested to be correlated with metastasis development." (PMID 32295254, 2020). "However, CDKN2A could be considered the critical tumor suppressor, as it is more commonly subject to single nucleotide variants and small insertions/deletions." (PMID 32242058, 2020). "Notably, CCND1 and CDKN2A alterations were only found in the HPV-negative tumor samples." (PMID 30934880, 2019).